SERPINB4 (serpin family B member 4)
Diseases named in the same sentence as SERPINB4 in open-access papers (continued):
Sharing a sentence is not in itself a finding about the gene and the disease.
tumor (24 papers, 2004 to 2026). "SERPINB4 is expressed at high levels in many tumor cells, and is known to inactivate granzyme M, an enzyme involved in tumor cell death." (PMID 30038719, 2018). "SERPINB4 staining intensity, as well as the percentage of SERPINB4 positive tumor cells, was compared between HPV-positive and HPV-negative OPSCC." (PMID 26993499, 2016). "Recent data demonstrated that overexpression of SERPINB4 in tumor cells inhibited recombinant granzyme M-induced as well as NK cell-mediated cell death." (PMID 24710357, 2014). "It has been reported that both serpinB3 and serpinB4 protect neoplastic cells from apoptosis and that serpinB3 promotes tumour growth, epithelial to mesenchymal transition and cell proliferation." (PMID 22808225, 2012). "Serological studies have reported elevated serum levels of serpinB4 isoform, ascribed to direct release from tumour cells." (PMID 22808225, 2012). "Overexpression of SERPINB4 in tumor cells inhibited recombinant GrM-induced as well as NK cell-mediated cell death and this inhibition depended on the reactive center loop of the serpin." (PMID 21857942, 2011). "We provide in vitro evidence that overexpression of SERPINB4 inhibits both GrM-induced and NK cell-mediated cell death in tumor cells." (PMID 21857942, 2011). "In conclusion, SERPINB4 inhibits GrM-mediated cleavage of the natural macromolecular substrates α-tubulin and nucleophosmin in a tumor cell lysate." (PMID 21857942, 2011). "GrM and SERPINB4 were incubated at various concentration-ratios and GrM-activity towards two known direct GrM-substrates in a Jurkat tumor cell lysate was determined by immunoblotting." (PMID 21857942, 2011). "In addition, anti-cancer immune-related genes were observed, e.g., SERPINB4 is highly expressed in cancer cells and inactivates anti-tumor enzymes such as granzyme M." (PMID 38203315, 2023). "The protein of SERPINB4 can inactivate granzyme M, an enzyme that kills tumor cells." (PMID 35439935, 2022). "This indicates that expression of SERPINB4 is beneficial for tumor cells." (PMID 21857942, 2011). "Moreover, mutations in SERPINB3 (16% vs. 3%, p < .001) and SERPINB4 (13% vs. 4%, p < .01) were more frequent in high ITS than low ITS group, which might promote serpin protein misfolding to increase tumor immunogenicity." (PMID 32969604, 2020). "The members of the family of the serine‐protease inhibitors (SERPINS), B3(SERPINB3) and B4(SERPINB4), are also respectively known as squamous cell carcinoma antigen‐1(SCCA1) and SCCA2 and were originally discovered as tumor‐specific antigens." (PMID 40995892, 2025). "Nevertheless, SERPINB4 and HRNR appeared in the “Neoplasia of cells” list identified by the IPA software evaluation of gene pathways of interest." (PMID 35085295, 2022). "In this study, we compared tumor-infiltrating CD3+, CD4+, CD8+ T-cells, and granzyme inhibitors (SERPINB1, SERPINB4, and SERPINB9) between HPV-positive and HPV-negative tumors and the relation with survival." (PMID 26993499, 2016). "SERPINB4 and SERPINB3 are serine protease inhibitor to modulate the host immune response against tumor cells." (PMID 20377895, 2010). "Low SERPINB3 and SERPINB4 expression was correlated with prolonged PFS, accompanied by the significant downregulation of gene sets involved in DNA replication, nonsense-mediated mRNA decay, and protein translation in long-PFS tumours." (PMID 42079393, 2026).
cancer (14 papers, 2009 to 2025). A tumor composed of atypical neoplastic, often pleomorphic cells that invade other tissues. "Finally, within the list of upregulated genes in the UCHL1 KD we also found several cancer-associated genes such as SERPINB4, FGF21, NUPR1, SBSN, GDF1, HMOX1, or SOCS2, which suggested the activation of potential compensatory mechanisms in these KDs cells." (PMID 28472177, 2017). "Studies have found that SERPINB3/SERPINB4 can promote the migration and invasion ability of cancer cells, and participate in the process of cell aging and inflammatory response." (PMID 36999136, 2023). "SERPINB4 can promote the migration and invasion of cancer cells, and participate in the process of cell senescence and inflammatory reaction." (PMID 36999136, 2023). "SERPINB4 is another important cancer-related gene, which is mutated in 53% of SC5 samples and no mutation in other subtypes." (PMID 35439935, 2022).
SERPINB4 also shares sentences with these, for which no sentence is quoted: atopic dermatitis (6 papers); cervical cancer (2); cervical tumor (2); head and neck cancer (2); infection (2); liver cancer (2); adenocarcinoma (1); allergic asthma (1); allergic rhinitis (1); amoebiasis (1); bacterial infection (1); bronchitis (1); cervical squamous cell carcinoma (1); chronic hepatitis (1); chronic obstructive pulmonary disease (1); conjunctivitis (1); contact dermatitis (1); COVID-19 (1); emphysema (1); eosinophilic esophagitis (1); epidermolysis bullosa simplex (1); esophageal cancer (1); genetic diseases (1); hepatocellular carcinoma (1); liver disease (1); Lymphatic Metastasis (1); Oral Cancer (1); parasite infection (1); respiratory diseases (1); Salmonella Infections (1).
A further 3 diseases each share a sentence with SERPINB4 in 1 paper.